SLC25A34 (solute carrier family 25 member 34)
Description:
Putative antiporter that exchanges dicarboxylates and sulfur oxoanions across the inner membrane of mitochondria.
Synonyms: DKFZp781A10161
Tractability: Antibody: UniProt predicts a signal peptide or a membrane-spanning region.
Gene: Protein-coding gene on chromosome 1 (15,736,176 to 15,741,392, forward strand). Ensembl gene ENSG00000162461.
Subcellular location: Mitochondrion inner membrane
Subcellular location (Human Protein Atlas): Mitochondria
Gene Ontology:
Cellular component: mitochondrial inner membrane
Genetic constraint (gnomAD): Loss-of-function variants: 29 observed, 30.82 expected, observed/expected ratio (o/e) 0.94, 90% interval 0.7 to 1.28. The upper end of that interval is the gene's LOEUF score, 1.28, which puts it in group 5 of 6, group 1 being the genes least tolerant of losing a copy. Missense variants: 384 observed, 368.69 expected, observed/expected ratio (o/e) 1.04, 90% interval 0.96 to 1.13. Synonymous variants: 182 observed, 161.88 expected, observed/expected ratio (o/e) 1.12, 90% interval 1 to 1.27.
Homologues: Orthologues: chimpanzee SLC25A34 (99% identical), macaque SLC25A34 (97% identical), guinea pig SLC25A34 (89% identical), rat Tmem82 (89% identical), mouse Slc25a34 (88% identical), pig SLC25A34 (83% identical), dog SLC25A34 (79% identical), Drosophila melanogaster CG8323 (44% identical), Drosophila melanogaster CG18324 (42% identical), tropical clawed frog slc25a34 (42% identical), Drosophila melanogaster CG18327 (42% identical), zebrafish slc25a34 (29% identical). Paralogues in human: SLC25A35 (50% identical), UCP3 (29% identical), UCP2 (29% identical), SLC25A12 (28% identical), SLC25A47 (28% identical), SLC25A13 (27% identical), UCP1 (27% identical), SLC25A48 (27% identical), SLC25A11 (25% identical), SLC25A21 (25% identical), SLC25A45 (25% identical), SLC25A1 (24% identical), and 37 more.
Diseases named in the same sentence as SLC25A34 in open-access papers:
SLC25A34 is named in the same sentence as 4 diseases in open-access papers, as found by Europe PMC text mining. Sharing a sentence is not in itself a finding about the gene and the disease.
SLC25A34 shares sentences with these, for which no sentence is quoted: autism (1 paper); colon cancer (1); neurodevelopmental disorder (1); tumor (1).